FOXI1 (forkhead box I1)
Diseases named in the same sentence as FOXI1 in open-access papers (continued):
Sharing a sentence is not in itself a finding about the gene and the disease.
salivary gland neoplasm (1 paper, 2024). Tumors of the SALIVARY GLANDS. "In this study, we tested this hypothesis for salivary gland tumors using immunohistochemistry (IHC) for FOXI1 and POU2F3 because, as mentioned, both ionocytes and tuft cells are found in salivary glands." (PMID 38358561, 2024). "Instead, we believe that WTs characteristically have the strongest capacity to produce FOXI1- and POU2F3-positive cells among common salivary gland tumors." (PMID 38358561, 2024). "Finally, we statistically compared the expression status of FOXI1 and POU2F3 among different salivary gland tumors." (PMID 38358561, 2024).
sensorineural deafness (1 paper, 2013). "Moreover, Foxi1 null mice showed phenotypic features of sensorineural deafness due to the defective pendrin-chloride mediated reabsorption in which FOXI1 was most likely a key regulator." (PMID 23965030, 2013).
tumor (12 papers, 2017 to 2024). "Dual staining of principal cell marker L1CAM and intercalated cell markers LINC01187/FOXI1 confirmed that L1CAM and LINC01187/FOXI1 were expressed in a mutually exclusive pattern in most tumor cells in HOT." (PMID 37994665, 2024). "The FOXI1-positive cells in the WTs appeared to have slightly less cytoplasm than the surrounding tumor cells and were located on the luminal side when the tumor formed cystic or glandular structures." (PMID 38358561, 2024). "The expression of FOXI1, which were only seen in WTs and PAs, were significantly different between WTs and the other seven tumor types (P < 0.01) and between PAs and the other seven tumor types (P < 0.05)." (PMID 38358561, 2024). "One of the most interesting pathways of miR-491-5p as a tumor suppressor is by targeting the Wnt3/β-catenin pathway mediated via Foxi1." (PMID 34590612, 2021). "Previous tumor cell studies found that the Foxi1 protein, belonging to the forkhead gene family, is a potential upstream regulator of miR-491-5p, and can bind to miR-491-5p binding sites to regulate the expression of miR-491-5p." (PMID 34660709, 2021). "Second, this is the first study to report the tumor suppressor role of Foxi1 by transcriptional regulation of miR-491-5p in the progression of GC." (PMID 28358374, 2017). "Because the proportion of immunoreactive cells and the H-scores for FOXI1 and POU2F3 were generally low, even in WTs, we cannot state that the tumor cells in WTs diffusely express FOXI1 and POU2F3." (PMID 38358561, 2024). "The observed mutually exclusive expression of two master regulators, FOXI1 and POU2F3, in different cell types in WTs seems unusual for a true (i.e., clonal) neoplasm and is consistent with the idea that WT is a reactive lesion." (PMID 38358561, 2024). "While CCND1 and FOXI1 were enriched in the nuclei, GPNMB showed a homogeneous and moderate/strong expression within the cytoplasmic compartment of the chRCC tumor cells, and MAPRE3 protein showed a predominant membranous expression pattern in RO." (PMID 38703764, 2024). "Nuclear FOXI1 staining occurred in 96% of 83 ROs, in 3% of 90 chRCCs, and in none of the other tumor types." (PMID 36810541, 2023). "The tumour cells were also positive for GATA3, E-cadherin, Pax-8, Succinate dehydrogenase B (SDHB) and Fumarate hydratase (FH), and negative for vimentin, Carbonic anhydrase 9 (CA9), CD10, P504s, CK20, TFE3, TFEB, HMB45, ALK and Forkhead box protein I1 (FOXI1)." (PMID 36816543, 2023). "All tumour cells were negative for vimentin, CA9, CD10, P504s, CK20, TFE3, TFEB, HMB45, ALK and FOXI1." (PMID 36816543, 2023).
cancer (7 papers, 2017 to 2026). A tumor composed of atypical neoplastic, often pleomorphic cells that invade other tissues. "Mucociliary ISCs are important for efficient mucociliary clearance, and Foxi1 dysregulation is linked to a range of human diseases affecting airway and kidney function as well as to causing deafness and cancers." (PMID 41490055, 2026). "In contrast, Foxi1 overexpression is found in cancer subtypes, e.g., in chromophore renal cell carcinoma and in pulmonary large cell carcinoma, but how Foxi1 overactivation can lead to cancerous transformations remains unresolved." (PMID 41490055, 2026). "As both WTs and PAs are benign, the frequency of FOXI1 expression differed significantly between benign and malignant tumors (20/28 and 0/25, respectively, P < 0.001)." (PMID 38358561, 2024). "Based on these findings, we hypothesize that FOXI1 and CFTR are not only major regulators of lung ionocytes but also closely associate with CXCL1 cancer subpopulations." (PMID 40568194, 2025). "Furthermore, FOXI1 is selectively expressed in intercalated cells (ICs), the putative cellular origin of chRCC36,50 and is more highly expressed in chRCC than other cancer subtypes in the TCGA dataset." (PMID 36681680, 2023). "Another facet of “lineage ambiguity” was the strong expression of FOXI1 in tuft cell-like cancers of different histotypes because this is the master regulator of ionocytes, which regulate airway surface physiology by expressing characteristic functional molecules, such as CFTR in the lung." (PMID 36402755, 2022). "Hence, our finding that Foxi1 drives an MPP state during mucociliary epidermis development could serve as a starting point to better understand the role of Foxi1 in cancers and other alterations across mucociliary tissues." (PMID 41490055, 2026).
benign tumors (1 paper, 2024). "Thus, the presence of FOXI1-positive cells may suggest benign tumors in salivary glands and be of differential diagnostic value." (PMID 38358561, 2024). "Among the benign tumors, only WTs and PAs consistently expressed FOXI1 (10/10 and 9/10, respectively)." (PMID 38358561, 2024). "Because WTs and PAs are benign and consistently harbored FOX1- and POU2F3-positive cells, the frequencies of FOXI1 and POU2F3 expression were significantly higher in benign tumors than malignant ones, although our cases were not chronologically selected in this study." (PMID 38358561, 2024).
FOXI1 also shares sentences with these, for which no sentence is quoted: renal tubular acidosis (2 papers); adenoid cystic carcinoma (1); basal cell carcinoma (1); benign salivary gland tumors (1); epilepsy (1); esophageal cancer (1); fibrosis (1); goiter (1); infection (1); microcephaly (1); microphthalmia (1); pancreatic cancer (1); polycystic kidney disease (1); Pseudoxanthoma elasticum (1); renal carcinoma (1); thymic carcinoma (1); thymoma (1); Warthin tumor (1).